RNU6-277P (RNA, U6 small nuclear 277, pseudogene)
Gene: Small nuclear RNA gene on chromosome 11 (105,974,826 to 105,974,931, reverse strand). Ensembl gene ENSG00000252081.
Homologues: Orthologues: chimpanzee U6 (100% identical). Paralogues in human: RNU6-654P (67% identical), RNU6-968P (67% identical), RNU6-1075P (66% identical), RNU6-486P (66% identical), RNU6-1011P (65% identical), RNU6-338P (65% identical), RNU6-474P (65% identical), RNU6-1060P (64% identical), RNU6-1091P (64% identical), RNU6-1124P (64% identical), RNU6-1147P (64% identical), RNU6-1260P (64% identical), and 1281 more.